PGLS (6-phosphogluconolactonase)
Description:
Hydrolysis of 6-phosphogluconolactone to 6-phosphogluconate.
Synonyms: 6PGL; HEL-S-304
Tractability: PROTAC: ubiquitination databases record sites on it; its protein half-life has been measured.
Target class: Enzyme; Hydrolase
Gene: Protein-coding gene on chromosome 19 (17,511,620 to 17,521,288, forward strand). Ensembl gene ENSG00000130313.
Subcellular location: Cytoplasm
Subcellular location (Human Protein Atlas): Nucleoplasm; Cytosol
Pathways (Reactome):
Metabolism: Pentose phosphate pathway
Gene Ontology:
Molecular function: 6-phosphogluconolactonase activity; protein binding
Biological process: pentose-phosphate shunt; pentose-phosphate shunt, oxidative branch; carbohydrate metabolic process
Cellular component: cytosol; extracellular exosome; nucleoplasm; cytoplasm
Genetic constraint (gnomAD): Loss-of-function variants: 21 observed, 18.34 expected, observed/expected ratio (o/e) 1.14, 90% interval 0.81 to 1.64. The upper end of that interval is the gene's LOEUF score, 1.64, which puts it in group 6 of 6, group 1 being the genes least tolerant of losing a copy. Missense variants: 408 observed, 306.52 expected, observed/expected ratio (o/e) 1.33, 90% interval 1.23 to 1.45. Synonymous variants: 177 observed, 144.27 expected, observed/expected ratio (o/e) 1.23, 90% interval 1.09 to 1.39.
Homologues: Orthologues: chimpanzee PGLS (99% identical), macaque PGLS (98% identical), dog PGLS (97% identical), mouse Pgls (89% identical), rat Pgls (89% identical), guinea pig PGLS (88% identical), pig PGLS (86% identical), tropical clawed frog pgls (61% identical), zebrafish pgls (59% identical), Drosophila melanogaster Pgls (41% identical), Caenorhabditis elegans Y57G11C.3 (31% identical).
Diseases named in the same sentence as PGLS in open-access papers:
PGLS is named in the same sentence as 16 diseases in open-access papers, as found by Europe PMC text mining. Sharing a sentence is not in itself a finding about the gene and the disease. The quoted sentences say what the papers report.
breast carcinoma (4 papers, 2020 to 2022). "Four proteins (FANCD2, EEF1A1, YWHAE, PGLS) have PPIs with at least one protein in all signatures and one protein in the breast cancer signature (ALDOC) interacts with all other four signatures." (PMID 36329531, 2022). "For example, the expression of glucose-6-phosphate dehydrogenase (G6PD) and 6-phosphogluconolactonase (6PGL) were elevated, implying a more activated PPP in HER2 subtype than other subtypes of breast cancer." (PMID 33489906, 2020). "Previous reports have shown that PGLS has a significant correlation with the occurrence of breast cancer, but its relationship with HCC has not been reported, whereas Huh7 and Hep3b cell lines that knock down PGLS have decreased proliferation and metastasis and increased apoptosis in HCC cells." (PMID 34765603, 2021).
glioblastoma (2 papers, 2021 to 2022). The most malignant astrocytic tumor (WHO grade IV). "Here, we show that PGLS silencing in glioblastoma cells reduces steady-state levels of NADPH and GSH and increases levels of ROS, an effect that is linked to reduced clonogenicity." (PMID 33937017, 2021). "In order to determine whether PGLS plays a role in the generation of NADPH and the maintenance of GSH levels, we examined the effect of silencing PGLS in U87, U251 and GS2 glioblastoma cells on steady-state levels of NADPH and GSH." (PMID 33937017, 2021).
cervical cancer (1 paper, 2022). A primary or metastatic malignant neoplasm involving the cervix. "Further, to explore potential cellular targets for mycoepoxydiene in cervical cancer, Jin found that PGLS was significantly down‐regulated after treatment of mycoepoxydiene, suggesting that PGLS is a potential molecular target of mycoepoxydiene for treatment of cervical cancer." (PMID 34953081, 2022).
Cirrhosis (1 paper, 2018). A chronic disorder of the liver in which liver tissue becomes scarred and is partially replaced by regenerative nodules and fibrotic tissue resulting in loss of liver function. "For the oxidative phase of PPP enzymes, high G6PD mRNA expression levels were found to be associated with a progression of cirrhosis to HCC and reduced survival rate (P = 0.0209), while PGLS and PGD show no differential expression (P > 0.050)." (PMID 30430110, 2018).
gastric cancer (1 paper, 2022). A primary or metastatic malignant neoplasm involving the stomach. "The results of immunohistochemistry showed that PGLS was strongly expressed in gastric cancer tissues compared with those in adjacent tissues." (PMID 34953081, 2022). "Moreover, from Oncomine database analysis, PGLS was overexpressed in gastric cancer compared with that in normal gastric mucosa with 1.523‐fold change (p = 0.013)." (PMID 34953081, 2022). "The overexpression of PGLS predicts worse overall survival (OS) and post‐progression survival (PPS) for gastric cancer (OS, HR = 1.48, p = 2.1e‐05; PPS, HR = 1.35, p = 0.015)." (PMID 34953081, 2022).
ischemic stroke (1 paper, 2025). A stroke disorder caused by obstruction of blood flow to the brain, due to thrombotic (local blood clot formation) or embolic (due to a blood clot or other material traveling from another site) event. "Despite their known roles in cellular metabolism, the direct involvement of DBI, PGLS, GYG1, and TALDO1 in ischemic stroke remains scarce, warranting further investigation into their potential roles in stroke pathophysiology." (PMID 41342963, 2025).
memory impairment (1 paper, 2019). "Thus, the MWM results indicate that overexpression of PGLS induced memory impairment." (PMID 31779658, 2019).
promyelocytic leukaemia (1 paper, 2016). "Interestingly, depletion of enzymes in oxidative PPP, i.e. G6PD, PGLS (6-phosphogluconolactonase), and PGD, dramatically abrogated the proliferation of HL-60, a human promyelocytic leukaemia cell line." (PMID 27586085, 2016).
renal carcinoma (1 paper, 2021). A carcinoma arising from the epithelium of the renal parenchyma or the renal pelvis. "The high expression of GAPDH, PSAT1, PGLS, and LDHC indicated a short DFS and a high risk of developing renal cancer." (PMID 33564363, 2021).
tumor (4 papers, 2021 to 2026). "G6PD (6-Phosphogluconate dehydrogenase), PGLS (6-phosphogluconolactonase), and 6PGD (6-phosphogluconate dehydrogenase) catalyze the oxidative PPP branch, which is closely linked to tumor growth." (PMID 36755301, 2023). "However, the precise contribution to redox and tumor proliferation of the second PPP enzyme 6-phosphogluconolactonase (PGLS), which converts 6-phospho-δ-gluconolactone to 6-phosphogluconate (6PG), remains unclear." (PMID 33937017, 2021). "Regarding the PPP, knockdown of PGLS, but not G6PDH or 6PGDH, significantly affected tumor growth." (PMID 40822358, 2025).
cancer (2 papers, 2016 to 2022). A tumor composed of atypical neoplastic, often pleomorphic cells that invade other tissues. "In general, the associations between Carbon Metabolism and Pathway in Cancer genes become weaken in HCC, whereas the associations between a number of genes are enhanced, especially those in the 22 up-regulated carbon metabolism genes group (such as HK1, PGK1, ENO1, PGLS, RPE)." (PMID 27363021, 2016).
infectious disease (1 paper, 2023). A disorder directly resulting from the presence and activity of a microbial, viral, or parasitic agent in humans. "This research strategy is also applicable to other PGCT systems (e.g., PglB and PglS) and is expected to be applied in the future for preparing conjugate vaccines for other anti-infectious diseases." (PMID 37149632, 2023).
PGLS also shares sentences with these, for which no sentence is quoted: lung carcinoma (1 paper); malaria (1); meningioma (1); Stroke (1).